RNA5S4 (RNA, 5S ribosomal 4)
Synonyms: RN5S4
Gene: Ribosomal RNA gene on chromosome 1 (228,616,991 to 228,617,109, reverse strand). Ensembl gene ENSG00000200381.
Gene Ontology:
Molecular function: structural constituent of ribosome
Cellular component: ribosome
Homologues: Orthologues: guinea pig 5S_rRNA (100% identical), macaque 5S_rRNA (100% identical), mouse n-R5s104 (100% identical), pig 5S_rRNA (100% identical). Paralogues in human: RNA5S1 (100% identical), RNA5S10 (100% identical), RNA5S11 (100% identical), RNA5S12 (100% identical), RNA5S13 (100% identical), RNA5S14 (100% identical), RNA5S15 (100% identical), RNA5S16 (100% identical), RNA5S17 (100% identical), RNA5S2 (100% identical), RNA5S3 (100% identical), RNA5S5 (100% identical), and 26 more.